TFDP1 (transcription factor Dp-1)
Description:
Can stimulate E2F-dependent transcription. Binds DNA cooperatively with E2F family members through the E2 recognition site, 5'-TTTC[CG]CGC-3', found in the promoter region of a number of genes whose products are involved in cell cycle regulation or in DNA replication. The E2F1:DP complex appears to mediate both cell proliferation and apoptosis. Blocks adipocyte differentiation by repressing CEBPA binding to its target gene promoters.
Synonyms: DRTF1; DP1; Dp-1; DILC
Tractability: PROTAC: UniProt records ubiquitination sites on it; ubiquitination databases record sites on it.
Target class: Transcription factor
Gene: Protein-coding gene on chromosome 13 (113,584,525 to 113,641,509, forward strand). Ensembl gene ENSG00000198176.
Subcellular location: Nucleus; Cytoplasm
Subcellular location (Human Protein Atlas): Nucleoplasm; Cytosol; Nuclear membrane
Pathways (Reactome):
Cell Cycle: Cyclin A:Cdk2-associated events at S phase entry; Cyclin D associated events in G1; Cyclin E associated events during G1/S transition; G0 and Early G1; G1/S-Specific Transcription; Inhibition of replication initiation of damaged DNA by RB1/E2F1; Transcription of E2F targets under negative control by DREAM complex; Transcription of E2F targets under negative control by p107 (RBL1) and p130 (RBL2) in complex with HDAC1
Cellular responses to stimuli: Oncogene Induced Senescence; Oxidative Stress Induced Senescence
Gene expression (Transcription): Transcriptional Regulation by E2F6
Programmed Cell Death: Activation of NOXA and translocation to mitochondria; Activation of PUMA and translocation to mitochondria
Signal Transduction: Pre-NOTCH Transcription and Translation; SMAD2/SMAD3:SMAD4 heterotrimer regulates transcription
Developmental Biology: Transcriptional regulation of granulopoiesis
Disease: Defective binding of RB1 mutants to E2F1,(E2F2, E2F3)
Gene Ontology:
Molecular function: DNA-binding transcription activator activity, RNA polymerase II-specific; DNA-binding transcription factor binding; protein binding; protein domain specific binding; RNA polymerase II transcription regulatory region sequence-specific DNA binding; DNA-binding transcription factor activity; DNA-binding transcription factor activity, RNA polymerase II-specific; cis-regulatory region sequence-specific DNA binding
Biological process: negative regulation of transcription by RNA polymerase II; positive regulation of G1/S transition of mitotic cell cycle; positive regulation of transcription by RNA polymerase II; regulation of DNA-templated transcription; transcription by RNA polymerase II; heterochromatin formation; negative regulation of DNA-templated transcription; negative regulation of fat cell proliferation; regulation of transcription by RNA polymerase II; regulation of cell cycle; regulation of gene expression
Cellular component: cytoplasm; nucleus; Rb-E2F complex; RNA polymerase II transcription regulator complex; RNA polymerase II transcription repressor complex; chromatin; DRM complex; nucleoplasm; PRC1 complex; transcription regulator complex
Genetic constraint (gnomAD): Loss-of-function variants: 6 observed, 48.4 expected, observed/expected ratio (o/e) 0.12, 90% interval 0.067 to 0.25. The upper end of that interval is the gene's LOEUF score, 0.25, which puts it in group 1 of 6, group 1 being the genes least tolerant of losing a copy. Missense variants: 335 observed, 560.41 expected, observed/expected ratio (o/e) 0.6, 90% interval 0.55 to 0.65. Synonymous variants: 201 observed, 218.28 expected, observed/expected ratio (o/e) 0.92, 90% interval 0.82 to 1.03.
Homologues: Orthologues: macaque TFDP1 (100% identical), mouse Tfdp1 (95% identical), rabbit TFDP1 (95% identical), dog TFDP1 (94% identical), guinea pig TFDP1 (94% identical), pig TFDP1 (93% identical), rat Tfdp1 (90% identical), chimpanzee TFDP1 (83% identical), zebrafish tfdp1a (80% identical), tropical clawed frog tfdp1 (77% identical), zebrafish tfdp1b (61% identical), Drosophila melanogaster Dp (42% identical), and 1 more. Paralogues in human: TFDP3 (74% identical), TFDP2 (64% identical).
Diseases named in the same sentence as TFDP1 in open-access papers:
TFDP1 is named in the same sentence as 44 diseases in open-access papers, as found by Europe PMC text mining. Sharing a sentence is not in itself a finding about the gene and the disease. The quoted sentences say what the papers report.
breast carcinoma (11 papers, 2009 to 2024). "Overexpression of TFDP1 has been associated with breast cancer and may also be linked to the tall stature, dysmorphism and dystonia seen in our patient." (PMID 23849371, 2013). "FOXA1, E2F3 and TFDP1 are also identified as miR‐522 targets by pulldown sequencing in breast cancer cells." (PMID 33369228, 2021). "It is amplified and overexpressed in breast cancer and upregulation of TFDP1 positively correlates with tumor size and progression of hepatocellular carcinomas and increased cell viability in lung cancer." (PMID 24564251, 2013). "The lack of correlation between TFDP1 and E2F1 expression suggests that TFDP1 may have a function in addition to gene transcription regulation and cell cycle progression in breast cancer." (PMID 19995430, 2009). "These genes include: transcription factor Dp-1 (TFDP1), cullin 4A (CUL4A), and cell division cycle 16 (CDC16) identified in hepatocellular carcinoma (HCC), breast cancer, and lung cancer; and insulin receptor substrate 2 (IRS2) present in colorectal cancer." (PMID 26684807, 2015). "Amplification of TFDP1 contributing to gene overexpression was reported in HCC, breast cancer, and lung cancer." (PMID 26684807, 2015). "TFDP1 is involved in the cell cycle and contributes to hepatocellular carcinomas, SMAD1 is involved in multiple pathways, and QSOX1 plays roles in some cancers such as breast cancer and neuroblastoma." (PMID 29686831, 2018). "We conclude that 13q34 amplification may be of relevance in tumor progression of basal-like breast cancers by inducing overexpression of CUL4A and TFDP1, which are both important in cell cycle regulation." (PMID 19995430, 2009). "In addition, they described amplification of CUL4A (25.7%), LAMP1 (13.5%), TFDP1 (31.1%), and GAS6 (13.5%) by DNA qRT-PCR on a set of 74 human breast carcinomas." (PMID 19995430, 2009). "This genomic aberration could facilitate the tumor progression through the overexpression of driver/target genes such as TFDP1 and CUL4A, which are overexpressed not only in Amp13q34 tumors, but also in other breast cancer samples characterized by a high cell proliferation and aggressiveness." (PMID 19995430, 2009).
hepatocellular carcinoma (10 papers, 2009 to 2024). A malignant tumor that arises from hepatocytes. "Specifically, increased expression of TFDP1 has been linked to the enlargement of hepatocellular carcinoma, while its downregulation has been shown to inhibit the growth of Hep3B cells." (PMID 39337305, 2024). "Particularly in hepatocellular carcinoma, TFDP1 overexpression was substantially associated with disease progression." (PMID 24598828, 2014). "This discordance between E2F1 and TFDP1 protein levels was also described in non-Hodgkin lymphomas and in hepatocellular carcinomas, where only TFDP1 overexpression was associated with a larger tumor size." (PMID 19995430, 2009). "Moreover, TFDP1 overexpression has been related to progression of hepatocellular carcinomas, and together with activated HA-RAS, causes oncogenesis in rat embryo fibroblasts." (PMID 19995430, 2009). "In our study, breast tumors overexpressing TFDP1 had high expression of p16, cyclin E and cyclin B1, as described in hepatocellular carcinoma." (PMID 19995430, 2009). "In agreement with our findings, the downregulation of TFDP1 may inhibit cell growth, as reported in hepatocellular carcinoma." (PMID 34366863, 2021). "It has been shown that TFDP1, together with E2F1, is involved in regulating hepatocellular carcinoma cells through a knockdown experiment that confirmed a physical interaction of KPNA2 with E2F1 and TFDP1." (PMID 33124660, 2020). "Overexpression of FIR in hepatocellular carcinoma (HCC) promotes tumor progression and dedifferentiation by stimulating FBP expression through Transcription Factor DP1/E2F Transcription Factor (TFDP1/E2F1)." (PMID 38539439, 2024).
lung carcinoma (5 papers, 2013 to 2024). "TFDP1 amplification has been associated with lung cancer in a previous study and has been stated as a potential oncogene." (PMID 34796107, 2021). "We selected seven genes [4 unique genes (E2F6, TFDP1, SUV39H1, and HNRPD) for NSCLC and 3 genes (RBL1, IRF1, and HMGA1) for general events] for validation as diagnostic markers in lung cancer." (PMID 24564251, 2013). "Moreover, TFDP1 amplification has been described in lung cancer and esophageal squamous cell carcinomas." (PMID 39737401, 2024). "Down-regulation of TFDP1 reduces cell growth as demonstrated in HCC and lung cancer cell lines." (PMID 26684807, 2015). "Additionally, downregulation of RB1 in lung cancer is not able to repress TFDP1 activity, and therefore, in lung cancer, tumorigenesis is mediated through upregulation of E2F6 and TFDP1." (PMID 24564251, 2013).
colon cancer (4 papers, 2009 to 2022). "The TFDP1 gene in the TGF-β pathway demonstrated an association with colon cancer even though the TGF-β pathway overall did not." (PMID 29986644, 2018). "The equivalence of RPL32 and KRT20 as well as the downstream relation of TFDP1 and DHX32 to these two genes is a first step toward refining the architecture of the colon cancer invasiveness network." (PMID 19180177, 2009).
liver cancer (4 papers, 2019 to 2023). An epithelial or non-epithelial malignant neoplasm that arises from the liver. "Previous studies have demonstrated that overexpression of TFDP1 can promote tumor cell growth, thereby accelerating the progression and deterioration of certain liver cancers." (PMID 37517087, 2023). "Here, we identified by proteome-wide analysis that KPNA2 is required for maintaining stathmin overexpression in liver cancer cells and dissected the underlying regulatory mechanism involving the nuclear import of the transcription factors E2F1 and TFDP1." (PMID 31783876, 2019). "RT-qPCR showed that TFDP1, NDRG1, and FXR1 were expressed at higher levels in different liver cancer cell lines compared to normal liver cells." (PMID 37517087, 2023). "We used the GSE39791 dataset for validation and could see that the expression of TFDP1, NDRG1 and FXR1 in liver cancer tissues was significantly higher than that in normal tissues." (PMID 37517087, 2023).
breast tumors (3 papers, 2009 to 2020). "Cullin4A (CUL4A) and transcription factor Dp-1 (TFDP1) at the 13q34 chromosomal region show increased protein expression in breast tumors." (PMID 32824813, 2020).
colorectal cancer (3 papers, 2015 to 2024). A primary or metastatic malignant neoplasm that affects the colon or rectum. "Moreover, a recurrent frameshift mutation in TFDP1 has been reported in colorectal cancer." (PMID 26620706, 2015).
depression (2 papers, 2017 to 2025). "Through comprehensive molecular regulatory network analysis, transcription factors such as ATF1, IRF1, HBP1, DRAP1, TGIF2, and TFDP1 were identified as potential regulatory factors in depression, warranting further exploration." (PMID 40370590, 2025).
lung adenocarcinoma (2 papers, 2013). A carcinoma that arises from the lung and is characterized by the presence of malignant glandular epithelial cells. "Our results suggest that overexpression of HMGA1, E2F6, IRF1, and TFDP1 and downregulation or no expression of SUV39H1, RBL1, and HNRPD in blood is suitable for diagnosis of lung adenocarcinoma and squamous cell carcinoma sub-types of NSCLC." (PMID 24564251, 2013).
bronchiectasis (1 paper, 2025). Segmental, irreversible dilation of the bronchial tree resulting in the accumulation of secretions which leads to obstruction. "The present study provides novel insights into the molecular mechanisms underlying bronchiectasis by identifying TFDP1 and CDC27 as key genes that are upregulated in this chronic respiratory disease." (PMID 41458288, 2025). "To further investigate the relationship between TFDP1 and CDC27, we divided 71 patients with bronchiectasis into two groups based on the median expression level of TFDP1 (36 patients with high TFDP1 expression and 35 patients with low TFDP1 expression)." (PMID 41458288, 2025). "The results showed that TFDP1 expression in bronchiectasis was positively correlated with the BSI (r = 0.2904, p < 0.05)." (PMID 41458288, 2025). "High expression of TFDP1 was often accompanied by high expression of CDC27 in the bronchiectasis group." (PMID 41458288, 2025). "These PRGs were intersected with 45 upregulated DEGs in the bronchiectasis group to obtain the TFDP1‐related upregulated DEGs." (PMID 41458288, 2025). "In summary, the current study revealed that TFDP1 and CDC27 were highly expressed in the bronchiectasis group and highlighted the potential regulatory effects of TFDP1 on CDC27." (PMID 41458288, 2025). "TFDP1 expression was correlated with the bronchiectasis severity index (r = 0.2904, p < 0.05)." (PMID 41458288, 2025). "Therefore, this study aimed to investigate the expression and underlying molecular mechanisms of TFDP1 and CDC27 in bronchiectasis." (PMID 41458288, 2025). "After the currently recognized treatment of bronchiectasis, such as antibiotics, airway clearance, immune regulation, and other treatments, how TFDP1 and CDC27 change and whether some drugs that affect the cell cycle can be used to treat bronchiectasis need further research." (PMID 41458288, 2025). "In the GSE97298 dataset, the expression levels of TFDP1 and CDC27 in the bronchiectasis group were significantly higher than those in the control group (p < 0.01)." (PMID 41458288, 2025). "To verify the expression of TFDP1 and CDC27 in bronchiectasis, we measured their expression in the peripheral blood of patients with bronchiectasis at the mRNA level." (PMID 41458288, 2025). "Regulatory relationships were assessed using ChIP‐seq data (Cistrome DB), and pathway enrichment was performed using clusterProfiler to explore the potential molecular mechanisms of action of TFDP1 and CDC27 in non‐CF bronchiectasis." (PMID 41458288, 2025). "Concurrently, we analyzed the correlation between TFDP1 and CDC27 and other clinical indicators in bronchiectasis." (PMID 41458288, 2025). "To explore the molecular mechanisms of TFDP1 in bronchiectasis, we performed GO function and KEGG pathway analyses of the upregulated DEGs of TFDP1." (PMID 41458288, 2025). "TFDP1 and CDC27 were significantly upregulated in patients with bronchiectasis (p < 0.01) and exhibited a strong positive correlation (r = 0.6104, p < 0.0001)." (PMID 41458288, 2025). "We found that the expression of TFDP1 and CDC27 in the bronchiectasis group was higher than that in the control group (p < 0.01)." (PMID 41458288, 2025). "Transcription factor DP‐1 (TFDP1) and cell division cycle protein 27 (CDC27), which are implicated in tumorigenesis and cell cycle regulation, have not been explored in bronchiectasis." (PMID 41458288, 2025). "This study focuses on the changes in the expression levels of TFDP1 and CDC27 in bronchiectasis and their clinical significance and explores the molecular mechanisms of their mutual regulation in the occurrence and development of bronchiectasis." (PMID 41458288, 2025). "Our study also explored cell cycle regulation, which may be an important mechanism by which TFDP1 and CDC27 participate in bronchiectasis development." (PMID 41458288, 2025).
bronchiectasis (continued). "This study demonstrated the synergistic upregulation of TFDP1 and CDC27 in bronchiectasis and explored cell cycle regulation as an important potential mechanism by which TFDP1 and CDC27 contribute to the development of bronchiectasis." (PMID 41458288, 2025). "Our findings demonstrated that both chip datasets and clinical samples showed that TFDP1 and CDC27 were significantly overexpressed in peripheral blood samples of patients with bronchiectasis compared with healthy controls, with a strong positive correlation between their expression levels." (PMID 41458288, 2025). "The roles of TFDP1 and CDC27 in diseases were mostly concentrated in tumor‐related diseases, but the roles in bronchiectasis have not been reported." (PMID 41458288, 2025). "However, the expression of TFDP1 and CDC27 in bronchiectasis and their relationship have not yet been reported." (PMID 41458288, 2025).
COVID-19 (1 paper, 2024). A disease caused by infection with severe acute respiratory syndrome coronavirus 2. "Similarly, we found the relevant evidence of alteration or association of transcription factors CENPA, DDIT3, JUNB, TFDP1, ZBTB16, ZNF467 for the alteration of diverse cellar process and function to develop the COVID-19 pathogenesis and associated respiratory disorders." (PMID 38365632, 2024).
Dystonia (1 paper, 2013). An abnormally increased muscular tone that causes fixed abnormal postures. "In our patient with dystonia and dysmorphism, it is possible that the presence of the breakpoint within the upstream promoter region of TFDP1 (NM_007111.4) is responsible for altered expression of this transcription factor." (PMID 23849371, 2013). "This is the first report to describe a potential connection between TFDP1 and dystonia." (PMID 23849371, 2013).
endometriosis (1 paper, 2021). The growth of functional endometrial tissue in anatomic sites outside the uterine body. "TFDP1, which encodes a protein that controls the G1/S phase of the cell cycle, is downregulated in women with endometriosis." (PMID 34281203, 2021).
follicular lymphoma (1 paper, 2021). Follicular lymphoma is a form of non-Hodgkin lymphoma characterized by a proliferation of B cells whose nodular structure of follicular architecture is preserved. "TFDP1 can be candidate master regulators contributing to follicular lymphoma progression." (PMID 34285141, 2021).
hip osteoarthritis (1 paper, 2021). "Knockdown of TFDP1 reduced both PITX1 promoter activity and mRNA transcription which caused patients suffering of knee/hip osteoarthritis." (PMID 34285141, 2021).
intrahepatic cholangiocarcinoma (1 paper, 2015). A carcinoma that arises from the intrahepatic bile duct epithelium in any site of the intrahepatic biliary tree. "We examined two iCCA cell lines and 86 cases of intrahepatic cholangiocarcinoma to analyze copy number of three target genes, including cullin 4A (CUL4A), insulin receptor substrate 2 (IRS2), and transcription factor Dp-1 (TFDP1) at 13q34 by quantitative real-time polymerase chain reaction." (PMID 26684807, 2015).
Lewy body dementia (1 paper, 2019). A progressive form of dementia characterized by the presence of protein deposits called Lewy bodies in the midbrain and cerebral cortex, and loss of cholinergic and dopaminergic neurons. "TFDP1 (targeted by miR-30b-5p and miR-365a-3p) is also associated with NFTs in AD, and EYA2 (targeted by miR-219) has been associated with brain pathologies seen in Lewy body dementia." (PMID 31037649, 2019).
myeloid leukemia (1 paper, 2024). A clonal proliferation of myeloid cells and their precursors in the bone marrow, peripheral blood, and spleen. "For this, we extracted the lists of DEGs in Tfdp1-KO mouse HSPCs, E2f4-KO mouse embryonic stem cells (ES cells; GSE109684), and TFDP1-KO human HAP cells (myeloid leukemia cell line; GSE144453)." (PMID 39043964, 2024).
nasopharyngeal carcinoma (1 paper, 2016). A carcinoma arising from the nasopharyngeal epithelium. "Overexpression of stathmin is strongly related to tumor aggressiveness of nasopharyngeal carcinoma patients, which attributes to the transactivation of transcription factor 1 (E2F1) and/or transcription factor Dp-1 (TFDP1)." (PMID 27670291, 2016).